LRRC4B (leucine rich repeat containing 4B)
Description:
Synaptic adhesion protein. Regulates the formation of excitatory synapses. The trans-synaptic adhesion between LRRC4B and PTPRF regulates the formation of excitatory synapses in a bidirectional manner (By similarity).
Synonyms: NGL-3; LRIG4; DKFZp761A179; HSM
Tractability: Small molecule: it belongs to a druggable protein family. Antibody: its Gene Ontology location is reachable by antibodies, with high confidence; UniProt places it where antibodies can reach, with medium confidence; UniProt predicts a signal peptide or a membrane-spanning region. PROTAC: its protein half-life has been measured.
Gene: Protein-coding gene on chromosome 19 (50,516,892 to 50,568,435, reverse strand). Ensembl gene ENSG00000131409.
Subcellular location: Membrane; Presynaptic cell membrane
Pathways (Reactome):
Neuronal System: Receptor-type tyrosine-protein phosphatases
Gene Ontology:
Molecular function: protein binding; cell-cell adhesion mediator activity; signaling receptor binding
Biological process: positive regulation of synapse assembly; regulation of postsynaptic density assembly; regulation of presynapse assembly; synaptic membrane adhesion
Cellular component: glutamatergic synapse; plasma membrane; postsynaptic density membrane; cerebellar mossy fiber; membrane; presynaptic membrane
Genetic constraint (gnomAD): Loss-of-function variants: 1 observed, 2.88 expected, observed/expected ratio (o/e) 0.35, 90% interval 0.12 to 1.5. That is too few expected variants to judge how well the gene tolerates losing a copy. Missense variants: 729 observed, 925.05 expected, observed/expected ratio (o/e) 0.79, 90% interval 0.74 to 0.84. Synonymous variants: 500 observed, 456.96 expected, observed/expected ratio (o/e) 1.09, 90% interval 1.02 to 1.18.
Homologues: Orthologues: chimpanzee LRRC4B (100% identical), macaque LRRC4B (99% identical), dog LRRC4B (98% identical), pig LRRC4B (98% identical), mouse Lrrc4b (96% identical), rat Lrrc4b (96% identical), guinea pig LRRC4B (80% identical), tropical clawed frog lrrc4b (75% identical), zebrafish lrrc4ba (68% identical), zebrafish lrrc4bb (65% identical), rabbit LRRC4B (58% identical). Paralogues in human: LRRC4C (57% identical), LRRC4 (50% identical), FLRT1 (19% identical), FLRT2 (18% identical), FLRT3 (17% identical), RTN4R (15% identical), LRRTM4 (15% identical), LRRTM3 (14% identical), NYX (14% identical), RTN4RL1 (14% identical), RTN4RL2 (14% identical), PODN (14% identical), and 10 more.
Diseases named in the same sentence as LRRC4B in open-access papers:
LRRC4B is named in the same sentence as 18 diseases in open-access papers, as found by Europe PMC text mining. Sharing a sentence is not in itself a finding about the gene and the disease. The quoted sentences say what the papers report.
breast carcinoma (2 papers, 2019 to 2021). "As a proof-of-concept to validate APSiC, we selected LRRC4B, a top putative tumor-suppressive effector in breast cancer, for functional validation." (PMID 34313788, 2021). "Our results provide compelling evidence that APSiC identified LRRC4B as a novel oncosuppressor gene in breast cancer." (PMID 34313788, 2021). "In the DRIVE RNAi screen, nearly all breast cancer cell lines displayed significantly increased cell viability upon LRRC4B knockdown and breast cancers in TCGA showed lower LRRC4B expression compared to normal breast tissue." (PMID 34313788, 2021). "As a proof of concept, we functionally validated LRRC4B as a putative tumor-suppressive effector in breast cancer." (PMID 34313788, 2021). "We functionally demonstrated that LRRC4B, a putative novel tumor-suppressive effector, suppresses proliferation by delaying cell cycle and modulates apoptosis in breast cancer." (PMID 34313788, 2021). "We selected the breast cancer cell lines MDA-MB231, BT-549 and MCF-7 with high, moderate and low endogenous LRRC4B expression to investigate whether modulating LRRC4B expression would result in other classical cancer phenotypes such as increased migration and colony formation." (PMID 34313788, 2021).
melanoma (1 paper, 2023). A malignant, usually aggressive tumor composed of atypical, neoplastic melanocytes. "The results showed that the expression of DSC3, DLL3, BMP6, SEMA4D, and GHRH are increased (p < 0.05) in melanoma, while the expression of LRRC4B, SFRP1, DCN, and CCL-8 decreased in melanoma (p < 0.05)." (PMID 36777724, 2023). "Then, we identified 9 LR pairs (“BMP6- > HJV” 、"CCL8- > ACKR4” 、"DLL3- > NOTCH3"、"DSC3- > DSG3"、"GHRH- > GHRHR” 、"LRRC4B- > PTPRF"、"SEMA4D- > PLXNB1"、"SFRP1- > FZD6"、"UCN- > CRHR1′′) as key LR pairs in melanoma prognosis through Lasso Cox regression and Multiple Stepwise Regression." (PMID 36777724, 2023).
brain disorder (1 paper, 2019). A disease affecting the brain or part of the brain. "It remains unknown whether mutations in the human LRRC4B gene encoding NGL-3 are associated with brain disorders." (PMID 31166939, 2019).
cancer (1 paper, 2021). A tumor composed of atypical neoplastic, often pleomorphic cells that invade other tissues. "A literature search of LRRC4B in cancer suggests that its role in carcinogenesis is unknown." (PMID 34313788, 2021).
tumor (1 paper, 2021). "However, we note that our in vitro experiments demonstrated that LRRC4B was, in fact, a tumor-suppressive effector." (PMID 34313788, 2021).
LRRC4B also shares sentences with these, for which no sentence is quoted: schizophrenia (2 papers); Alzheimer disease (1); Anxiety (1); attention deficit-hyperactivity disorder (1); autism (1); autism spectrum disorder (1); bipolar disorder (1); depression (1); multiple sclerosis (1); neurological diseases (1); obsessive-compulsive disorder (1); psychiatric disorder (1); restless leg syndrome (1).